IL2 (interleukin 2)
Diseases named in the same sentence as IL2 in open-access papers (continued):
Sharing a sentence is not in itself a finding about the gene and the disease.
colorectal cancer (continued). "First, we observed the distribution of T-cell growth factor IL-2 and T-cell activator IL-16 in the peripheral blood and found that IL-2 concentrations were increased in the peripheral blood of patients with stage IV colorectal cancer (one-way ANOVA, IL-2 control vs stage IV, p = 0.0226)." (PMID 37063892, 2023). "Consistently, we showed that, if given sufficient amount in the colorectal cancer model, the vaccine may release GM-CSF and IL-2 in a good timing and effectively elicited an autologous T cells response, which achieved high efficacy in preventing from the tumor formation." (PMID 27669687, 2016). "In the current study we addressed the question whether IL-2 treatment leads to an expansion of fully functional Treg cells in colorectal cancer patients and whether an increase of Treg cells in colorectal cancer patients is due to peripheral or thymic expansion." (PMID 22276195, 2012). "As Treg cells with a naïve phenotype were increased in patients with colorectal cancer, particularly post IL-2 treatment, we were interested to assess whether the increase of Treg cells resulted from peripheral expansion or possibly thymic generation of CD4+CD25highFOXP3+ Treg cells." (PMID 22276195, 2012). "It was observed that malignant effusion from colorectal cancer decreased or disappeared successfully in more than 80% patients when treated with a simple, easily administered streptococcal preparation OK-432 alone or in combination with T-cell growth factor IL-2." (PMID 14612896, 2003). "BIRC5-specific T lymphocytes which recognize colorectal cancer cells and BIRC5-specific class I HLA-restricted T lymphocytes were activated and released interleukin 2 in response to HLA/ BIRC5-peptide complexes expressed by tumor cells." (PMID 33431968, 2021). "For example, lyso-PS can provoke eosinophil degranulation via P2Y10, suppress IL-2 production by activated T cells via GPR174, and stimulate chemotactic migration and invasion of colorectal cancer cells via GPR34." (PMID 33875796, 2021). "Combination of IL-2/15/21 can enhance TIL expansion in lung and colorectal cancer and promote CD8+ T cell percentage as well as TCR clone diversity compared to IL-2 alone." (PMID 34112147, 2021). "For example, among 30 patients with colorectal cancer treated with LAK cells and IL-2, one complete anti-tumor immune response and four partial anti-tumor immune responses were seen." (PMID 21455282, 2011). "This phase II study was designed to evaluate the anti-tumour activity and toxicity of the combination of IL-2, IFN alpha-2a and 5-FU in patients with advanced colorectal cancer." (PMID 8980407, 1996). "This regimen of IL-2 and IFN alpha-2a with 5-FU has only modest anti-tumour activity in advanced colorectal cancer." (PMID 8980407, 1996). "Hence, the relative expression of the IL-1β, IL-2, CXCL8, and FN1 was overexpression by colorectal cancer and administration of 5-FU." (PMID 38637796, 2024). "In addition, the inflammation molecules (IL-17, IL-2, IL-18, and IL-13) and oxidative stress capacity (GPx and SOD) were dysregulated in colorectal cancer as well as administration of 5-FU." (PMID 38637796, 2024). "On the contrary, IFN-γ and IL-2 did not coexpress in individual single cells isolated from colorectal cancer specimens." (PMID 34321276, 2021). "In a study using preoperative IL-2, 86 colorectal cancer (CRC) patients with stage II/III disease were randomized to receive low dose IL-2 twice a day for 3 consecutive days before surgery or no treatment." (PMID 30176921, 2018). "To better evaluate and improve the efficacy of dendritic cell (DC)-based cancer immunotherapy, we conducted a clinical study of patients with advanced colorectal cancer using carcinoembryonic antigen (CEA)-pulsed DCs mixed with tetanus toxoid and subsequent interleukin-2 treatment." (PMID 27558635, 2016).
colorectal cancer (continued). "We have investigated the secretion of interferon alpha (IFN-alpha), IFN-gamma, interleukin-1alpha (IL-1alpha), IL-1beta, IL-2 and tumour necrosis factor alpha (TNF-alpha) in whole blood cell cultures (WBCCs) of colorectal cancer patients upon mitogen stimulation." (PMID 9792144, 1998). "Whereas the values for IL-1beta and TNF-alpha remained virtually unchanged in comparison with healthy control subjects, WBCCs of colorectal cancer patients secreted significantly lower amounts of IFN-alpha (P < 0.005), IFN-gamma (P < 0.0001), IL-1alpha (P < 0.0001) and IL-2 (P < 0.05)." (PMID 9792144, 1998). "We have analyzed this mechanism in colorectal carcinoma (CRC) and found that co-culture of NK cells with TAF can prevent the IL-2-mediated NKG2D upregulation." (PMID 29910806, 2018). "For example, in IBD immunocompromised patients, a reduced/lack of IL-2 activity could impair immune surveillance by antineoplastic lymphokine-activated killer or natural killer cells and may result in a higher risk for IBD-associated colorectal cancer." (PMID 33814980, 2021).
lymphopenia (68 papers, 1998 to 2026). Reduction in the number of lymphocytes. "Regarding this, it is possible that IL-2 deficiency, induced by lymphopenia, reduces the expansion and maintenance of Tregs and therefore favors greater proliferation of effector T cells and increasing IL-21 levels." (PMID 39124778, 2024). "In vitro, cortisol reduces mRNA levels of IL-1β, TNF-α, and IL-8, as well as IL-2 serum levels, causing lymphopenia during acute stress." (PMID 36425123, 2022). "Altered lymphocyte homeostasis 33, such as a progressive decline of IL‐2 34 in the blood concentrations, appears to be associated with lymphopenia." (PMID 26814381, 2016). "Demonstration of IL-7 dependent modulation of IL-2 signaling also provides a rationale for the association between T cell lymphopenia and Treg enrichment." (PMID 25485946, 2014). "The decrease in the number of producer cells due to lymphopenia results in a relative deficiency of IL-2, which may be an additional factor of Tregs’ decreased functional activity in vivo." (PMID 33809452, 2021). "Persistent lymphopenia could be considered to reduce synthesis of IL-2 and cause immune suppression." (PMID 24324972, 2013). "Cortisol induces rapid lymphocyte redistribution, causing a 20–40% lymphopenia by 24–48 h post-RWL and impairing T-cell-mediated responses through reductions of 30–50% in IL-2 and interferon (IFN)-γ synthesis upon mitogen challenge." (PMID 41516380, 2026). "Thrombocytopenia and lymphopenia are also commonly observed with HD IL-2 treatment and coincide with CLS." (PMID 39114660, 2024). "Expression of CD25 (an α chain of the high-affinity IL-2 receptor) indicates potential sensitivity to IL-2 and lymphopenia-mediated induction, the primary modulators for the development and maintenance of Tregs." (PMID 36389741, 2022). "This immunosuppression includes apoptosis-induced lymphopenia, decreased interleukin 2 (IL-2) secretion, neutrophil storm, impaired phagocytosis, and decreased monocyte human leukocyte antigen-DR." (PMID 35054900, 2022). "Steroid‐induced lymphopenia occurs via inhibition of T‐cell activation by inhibition of IL‐2, IL3, IL‐4, and IL‐6,43 and suppression of dendritic cell maturation and function." (PMID 35478442, 2022). "IL-2, IL-7 and IL-15 are three cytokines playing a role in the development, proliferation and survival of T cells that have been evaluated to restore lymphopenia." (PMID 30922400, 2019). "Multiple mechanisms has been suggested and documented to explain stress-induced lymphopenia, which include both decreased efflux from lymph nodes, and decreased proliferative and activation cytokines (e.g., IL-2) for lymphocytes." (PMID 31410314, 2019). "In contrast, Th1 development exhibited strong anti-correlation with Nur77-GFP reporter activity and PD-1 expression levels and instead correlated with T cell lymphopenia and the availability of IL-2, together likely driving T cell clonal expansion." (PMID 29951052, 2018). "Despite not being absolutely necessary for Treg expansion in lymphopenic setting, IL-2 and lymphopenia have been shown to synergize in the induction of Treg expansion after transfer into empty hosts." (PMID 25485946, 2014). "Consistent with the effects on immune function of exogenous IL2, PBMC counts decreased during the days of huKS-IL2 infusion, reflecting treatment-related lymphopenia/lymphocyte trafficking." (PMID 23320927, 2013). "The Selectikine treatment was associated with typical IL-2-like biological effects including lymphopenia followed by lymphocytosis and eosinophilia at all dose levels, while IL-2 related clinical AEs were mainly mild to moderate." (PMID 23294527, 2013). "Administration of IL-2 prior to surgery can prevent lymphopenia and provide possible survival benefit in pancreatic, colorectal, and gastric cancer." (PMID 22369276, 2012).
lymphopenia (continued). "IL‐2 is a growth factor and important cytokine for the survival and proliferation of Tregs and T effector cells, and therefore administrating low doses of recombinant IL‐2 in COVID‐19 patients should resolve lymphopenia and restore normal T‐cell counts." (PMID 32935333, 2021). "The release of chemokines such as CXCL-10/IP-10 and CCL-2/MCP-1 may also contribute to CD4 lymphopenia, mostly due to the suppression of hematopoietic progenitor cells proliferation, or to the inhibition of IL-2 signaling pathway." (PMID 34122423, 2021). "Our findings therefore provide strong support for the notion that such robust proliferative responses of naïve T cells can be easily driven by relatively increased levels of in vivo IL-2 produced from antigen-stimulated T cells in both situations of chronic and acute lymphopenia." (PMID 30190718, 2018). "When considering Treg homeostasis, such strategy could be especially relevant in context of ageing, a context of T cell lymphopenia in which IL-2 levels available are reduced." (PMID 25485946, 2014). "Furthermore, homeostatic cytokines such as IL-7 and IL-15, that are prevalent during lymphopenia, have been shown to be able to substitute for IL-2 signaling in activated effector cells." (PMID 22383993, 2012). "Peripheral expansion of CD4+CD25hi Treg in vivo is regulated by both IL-2 and lymphopenia." (PMID 19270751, 2009). "Thus, there is concern regarding the growth enhancing effect of IL-2 administration during lymphopenia." (PMID 19270751, 2009). "Although 3 days of subcutaneous IL-2 resulted in significant lymphopenia, evidence of immune activation was indicated by a significant rise in the percentage of CD56- (NK cells) and CD3/HLA-DR-positive (activated T cells) subsets, without any change in the percentage of CD4 or CD4 T-cell subsets." (PMID 9579834, 1998). "Yet, not only lymphopenia itself causes dysfunction of cellular immunity, but also an impaired stimulation of CD45RO T cells via the T cell receptor (TCR), which leads to decreased proliferation as well as IL-2 and IFN-γ production compared with healthy controls." (PMID 39165363, 2024). "Additionally, we found that IL-2 and IL-4 were elevated and exceeded the normal upper limit at the same time point of recovery of lymphopenia before discharge, indicating that they might be beneficial to the recovery process." (PMID 33461503, 2021). "Moreover, increased IL-2 and IL-7, which are the cytokines responsible for the expansion and differentiation of T cell subsets, may attempt to reverse lymphopenia and T cell exhaustion." (PMID 33365277, 2020). "As lymphopenia is typically characterized by increased levels of IL-7 and having shown that IL-7 availability increases Treg reactivity to IL-2, we speculated that IL-7 could affect IL-2 induced Treg expansion." (PMID 25485946, 2014). "Modeling based on IL-2 IC50 predicts up to 94% average daily inhibition at clinical dosage, which would suggest severe lymphopenia to be more prevalent with JAK1,2,3 inhibitor use." (PMID 39403378, 2024). "Asymptomatic carriers exhibited higher N-specific IgG4/IgG1 ratio and higher RBD-specific/N-specific IgG1 while symptomatic patients exhibited increased neutrophil counts and lymphocytopenia as well as higher TNF-α, IL-2, IL-8, and IL-12p70." (PMID 35685940, 2022). "Additionally, the significant reduction of IL-2 early after transplant suggests that previously reported Treg reconstitution may not be reliant on this cytokine, and may instead occur as a result of lymphopenia-induced homeostatic proliferation." (PMID 35126353, 2021). "IL-2, a key cytokine responsible for both CD4+ and CD8+ T cell proliferation, has been evaluated in HIV patients with severe CD4+ lymphopenia." (PMID 30922400, 2019).
lymphopenia (continued). "Notably, these observations were not limited to a unique environment of chronic lymphopenia but rather broadly applicable for various other acute lymphopenic conditions with two crucial requirements, namely antigen-dependent T cell activation and availability of relatively high amounts of IL-2." (PMID 30190718, 2018). "Given that CD28 and IL-2 play important roles in Treg function, the relationships between premature CD4+ T cell aging and lymphopenia as well as Treg defects in autoimmune-prone NOD mice are proposed." (PMID 24586733, 2014). "Adverse events included rash, fatigue, nausea and diarrhea, but patients had very rarely adverse events associated with capillary leak, such as hypotension, pyrexia, flu-like symptoms and peripheral edema and had no IL-2 related lymphopenia." (PMID 39114660, 2024). "Up-regulated levels of sCD25 may contribute to lymphopenia, which is an indicator of the severity and hospitalization in SARS-CoV-2 infection, through IL-2 signaling inhibition." (PMID 35233677, 2022). "The injection of high doses of IL-2, one of the first immunotherapies approved by the FDA as a single agent for treatment of metastatic melanoma and RCC, induced significant hematological toxicities including thrombocytopenia and lymphopenia." (PMID 30922400, 2019). "Although not strictly required for Treg proliferation during lymphopenia, IL-2 administration in this setting has been shown to strongly increase Treg expansion." (PMID 25485946, 2014). "Consistent with other IL2/cytokine-based therapies, these episodes of lymphopenia may not reflect myelosuppression, but are likely due to immunocytokine-induced lymphocyte trafficking to the peripheral tissues, including tumor beds or draining nodal tissues." (PMID 23320927, 2013). "Whilst this suggests that reduced IL-2 and its receptor may be preventing CD4+ proliferation and differentiation, therefore increasing the risk of post-operative infections, administration of therapeutic IL-2 following surgery did not prevent the initial lymphopenia." (PMID 41148718, 2025). "Although the vast majority of Vδ2 lymphocytes do not express CD4, in the setting of lymphopenia, rapid T-cell turnover, or heightened immune activation, increased IL-2 levels could lead to CD4 upregulation in Vδ2 cells, making them susceptible to HIV infection in vivo." (PMID 26473478, 2015). "However, administration of anti-IL-2Rα MAb during lymphopenia may function differently than in a normal non-lymphopenic context due to disparate IL-2 signaling requirements by regulatory versus effector T-cells." (PMID 22383993, 2012). "Interestingly, the elevated IL-10 in the serum was correlated with the appearance of lymphopenia during FMDV infection but not IL-6, IL-2, IL-17, IL-18, IL-1β, TNF-α, IFN-α/β, TGF-β, and CXCL1." (PMID 34960627, 2021).
capillary leak syndrome (63 papers, 2008 to 2026). A syndrome characterized by leakage of intravascular fluids into the extravascular space. "IL-2 is commonly associated with immune-related toxicities, such as capillary leak syndrome, whereas the primary toxicities of oxaliplatin and leucovorin are generally neurological, gastrointestinal, and hematological." (PMID 39773310, 2025). "It has been reported that high-dose IL-2 administration causes capillary leak syndrome, and, coincidentally, capillary leak syndrome is a severe clinical manifestation of CRS." (PMID 39359733, 2024). "The adverse effects associated with cytokine therapies, such as the capillary leak syndrome seen with high-dose IL-2 treatment, have necessitated the development of strategies to mitigate toxicity while preserving efficacy." (PMID 39034318, 2024). "For example, high-dose IL-2 has been known to induce fatal capillary leak syndrome, while IL-15 has been associated with hypotension, thrombocytopenia, and other adverse effects included." (PMID 38049832, 2023). "Prior reports have shown that a systemic administration of high‐dose IL‐2 is associated with treatment‐related mortality, including capillary leak syndrome in multiple organs." (PMID 36684086, 2023). "Causes of death were capillary leak syndrome (2×), in one case after an IL-2 overdose (medication error), sudden cardiac arrest, and acute respiratory distress syndrome in the context of an infection." (PMID 33680926, 2020). "The induction of nitric oxide as a consequence of IL-2 administration is thought to be responsible for immunotherapy-associated capillary leak syndrome and hypotension." (PMID 29967609, 2018). "The anti-cancer activity of IL-2 has long been known, and high-dose IL-2 can be toxic and is associated with capillary leak syndrome; thus, efforts to lower the toxicity have focused in part on lowering IL-224." (PMID 29123649, 2017). "Native IL-2 administration may cause death (2-4%) and capillary leak syndrome (CLS), characterized by extravasation of fluids and proteins." (PMID 40486521, 2025). "High doses of IL-2 are often associated with severe side effects when intravenously administered, including fever, chills, hypotension, oliguria, vomiting, acute episodes of capillary leak syndrome, significantly reduced neutrophil function, etc.." (PMID 38893211, 2024). "Additionally, IL-2 has been also associated with hemodynamic instability due to increased vascular permeability (capillary leak syndrome), and peripheral or pulmonary edema." (PMID 37355743, 2023). "However, treatment with HD IL-2 is associated with a high risk of serious adverse events, including capillary leak syndrome, hypotension, respiratory failure, oliguria, and anuria." (PMID 35053435, 2022). "However, systemic IL‐2 therapy can be difficult to tolerate, primarily due to serious side effects associated with capillary leak syndrome." (PMID 33152115, 2021). "We designed the present study to evaluate the manageability and tolerability of a therapeutic schedule consisting of a short HD IL-2 infusion repeated every 21 days, corticosteroids to reduce the risk of capillary leak syndrome, and RT to exploit the synergistic effect." (PMID 34777395, 2021). "Toxicities from the therapy were predominantly associated with lymphodepletion and high-dose interleukin 2 (IL-2), including grade 3 toxicities of neutropenia, anemia, thrombocytopenia, febrile neutropenia as a consequence of lymphodepletion, capillary leak syndrome, and hyperbilirubinemia." (PMID 34369137, 2021). "However, the IL-2 treatment component continued to cause severe inflammatory side effects with a rate of 13% of treated patients developing grade 3&4 capillary leak syndrome." (PMID 33392114, 2020). "Thus, IL-2 treatment was associated with adverse events including severe capillary leak syndrome that represent a major concern in IL-2 treatment." (PMID 28824651, 2017).